DSG2 (desmoglein 2)
Diseases named in the same sentence as DSG2 in open-access papers (continued):
Sharing a sentence is not in itself a finding about the gene and the disease.
Anxiety (2 papers, 2020 to 2024). Intense feelings of nervousness, tension, or panic often arise in response to interpersonal stresses. "To quantify PSS-induced by this behavioral paradigm, we measured anxiety levels in 14-week old male wildtype (WT) and Desmoglein-2 mutant (Dsg2mut/mut) mice, a robust mouse model of ACM, using the light-dark box (LDB) test over the course of two weeks." (PMID 33255451, 2020).
benign papillomas (2 papers, 2012 to 2015). "Moreover, Inv-Dsg2 transgenic mice also developed benign papillomas and were more susceptible to chemically induced two-stage skin carcinogenesis." (PMID 25785582, 2015). "Although the Inv-Dsg2 transgenic mice developed precancerous papillomas and were more susceptible to chemically induced carcinogenesis, the mechanism by which Dsg2 induces these changes remains unclear." (PMID 25785582, 2015). "In contrast, DSG2 expression is increased in some malignant skin carcinomas, and transgenic expression of Dsg2 in the differentiating layers of epidermis rendered mice susceptible to papilloma development, suggesting a pro-tumorigenic role for this desmosomal constituent." (PMID 23185521, 2012). "Upregulation of CSTA is also detected in another transgenic mouse model overexpressing the early gene region of the human papillomavirus type 8, these mice develop papillomas similar to our Inv-Dsg2 mice." (PMID 25785582, 2015).
bladder cancer (2 papers, 2005 to 2025). "We examined the constitutive expression levels of desmocollin-2 and desmoglein-2 in the panel of bladder carcinoma cell lines." (PMID 15942628, 2005).
colorectal adenocarcinoma (2 papers, 2013 to 2022). The most common type of colorectal carcinoma. "Dsg2 was also found to be important in another colorectal adenocarcinoma cell line, HT-29." (PMID 23326495, 2013).
colorectal cancer (2 papers, 2020). A primary or metastatic malignant neoplasm that affects the colon or rectum. "The loss of desmoglein-2 is thought to facilitate cell proliferation and growth by activating the Akt/beta-catenin signaling pathway, as shown in the colorectal cancer cell line." (PMID 33291824, 2020).
Crohn disease (2 papers, 2017 to 2022). A gastrointestinal disorder characterized by chronic inflammation involving all layers of the intestinal wall, noncaseating granulomas affecting the intestinal wall and regional lymph nodes, and transmural fibrosis. "Desmoglein 2 (Dsg2), an adhesion molecule of desmosomes and the only Dsg isoform expressed in enterocytes, is required for epithelial barrier properties and may contribute to barrier defects in Crohn’s disease." (PMID 28740231, 2017).
diabetes (2 papers, 2021 to 2022). "Modification of the F-actin network is key to islet cell function as it mediates insulin secretion and results here suggest that DSG2 is protective with loss of DSG2 in the Beta-TC-6 cells increasing the release of TNFα, a known pathogenic and proinflammatory cytokine implicated in diabetes." (PMID 36309486, 2022). "Genetically-modified mice lacking Dsg2 were examined for islet cell mass, insulin production, responses to glucose, susceptibility to a streptozotocin-induced mouse model of hyperglycaemia, and ability to cure diabetes in a syngeneic transplantation model." (PMID 36309486, 2022).
fibrosis (2 papers, 2022). the formation of excess fibrous connective tissue in an organ or tissue in a reparative or reactive process. "In the current study, the cardiac fibrosis of ACM and its underlying mechanism were investigated by using a cardiac-specific knockout of Dsg2 mouse model." (PMID 36291052, 2022). "Cardiac-specific Dsg2 deletion induces excessive cardiac fibrosis in mice." (PMID 36291052, 2022).
gall bladder cancer (2 papers, 2023 to 2025). "Dsg2 knockdown has also been shown to induce epithelial to mesenchymal transition in gall bladder cancer cells, and pro-EMT transcription factors (Snail) have been shown to increase Dsg2 degradation." (PMID 41244075, 2025). "In contrast, reports implicating an anti-tumorigenic function for DSG2 exist for cancers of the gallbladder, thyroid, and the stomach." (PMID 38188287, 2023).
influenza (2 papers, 2021 to 2023). An acute viral infection of the respiratory tract, occurring in isolated cases, in epidemics, or in pandemics; it is caused by serologically different strains of viruses (influenzaviruses) designated A, B, and C, has a 3-day incubation period, and usually lasts for 3 to 10 days. "Increased anti-DSG2 autoantibodies are not induced to all infections as evidenced by the relative absence of anti-DSG2 responses in other groups including a cohort of influenza patients." (PMID 37095599, 2023).
lung squamous cell carcinoma (2 papers, 2017 to 2020). "DSG2 was especially higher in lung squamous cell carcinoma (LUSC)." (PMID 33217893, 2020).
metastatic disease (2 papers, 2014 to 2016). "To validate these results and compare DSG2 expression in primary versus metastatic disease, we next evaluated whole tissue sections using a different anti-DSG2 mAb, clone 10G11." (PMID 27340778, 2016). "In the autopsy collections, one patient had uniformly DSG2+ disease while for the other two patients, only 5/6 and 2/5 of their metastatic tumors were DSG2+." (PMID 27340778, 2016). "We next investigated whether DSG2 expression varies temporally or spatially in patients with metastatic disease." (PMID 27340778, 2016). "Taken together these results may reflect the need for a re-expression of DSG2 in an aggressive cancer in order to establish the cell-cell adhesion necessary to form a metastatic tumor." (PMID 24896103, 2014). "For the majority of patients (6/8), the expression of DSG2 did not vary between their primary and metastatic tumors." (PMID 27340778, 2016).
Obesity (2 papers, 2019). Accumulation of substantial excess body fat. "It has been postulated that obesity leads to lipotoxic cardiomyopathy, interstitial fibrosis, and inflammation leading to dysfunctional desmosomal proteins such as Dsg2." (PMID 31024340, 2019).
prostate tumor (2 papers, 2014 to 2015). "Taken together these results suggest that DSG2 expression is reduced in primary prostate tumors with an aggressive biological behavior." (PMID 24896103, 2014). "Normal prostate epithelium was characterized by a high percentage of cells positive for DSG2 expression (mean expression of 81.1%, median of 84.5%), whereas prostate tumor samples showed a significantly lower percentage of DSG2 positive cells (mean expression of 57.5%, median of 66.7%; P = 0.0002)." (PMID 24896103, 2014). "Additionally, the retained expression of DSG2 in all the examined tumors suggests that the presence of DSG2-based desmosomal adhesion alone is not sufficient to support prostate tumor formation." (PMID 26033689, 2015).
acute myeloid leukemia (1 paper, 2025). Acute myeloid leukemia (AML) is a group of neoplasms arising from precursor cells committed to the myeloid cell-line differentiation. "To further explore DSG2 expression in NK cells within an oncological context, we analyzed single-cell RNA sequencing (scRNA-seq) data from NK cells isolated from the bone marrow of HD and patients with acute myeloid leukemia (AML)." (PMID 40607388, 2025).
acute T cell leukemia (1 paper, 2022). "As many cancers with hematopoietic cell origin show strongly upregulated DSG2 expression and present a potential target for oncolytic viral therapy, we also tested the transgene expression of our novel JO4 vectors in K562 (chronic myeloid leukemia) and Jurkat (acute T cell leukemia) cells." (PMID 36016457, 2022).
atherosclerosis (1 paper, 2019). A disease characterized by the build-up of fatty material and calcium deposition in the arterial wall resulting in partial or complete occlusion of the arterial lumen. "However, their involvement in atherosclerosis-related processes, such as cellular adhesion, neo-angiogenesis (DSG2, PSGs) and innate immunity (PSGs, CPNE7) suggests these proteins as potential atherosclerosis markers." (PMID 31242269, 2019).
blistering (1 paper, 2010). "Thus, finding a drug/agent that could increase Dsg2 levels in the skin or, preferably, activate the signaling pathways downstream of Dsg2 offers a potential therapeutic treatment for this life-threatening blistering disease." (PMID 20631906, 2010).
calcinosis (1 paper, 2011). Deposition of calcium in the tissues. "Although biochemical changes underlying this phenotype have not been extensively investigated in BALB/c mice themselves, a similar condition has been studied in mice expressing a mutant form of desmoglein 2 (lacking the extracellular adhesive domain), that develop cardiac fibrosis and calcinosis." (PMID 21829669, 2011).
cardiac sarcoidosis (1 paper, 2024). Sarcoidosis affecting the tissues of the heart. "For instance, anti-DSG2-abs have been found in other inflammatory cardiomyopathies, i.e., cardiac sarcoidosis, and showed a correlation with non-invasive imaging techniques demonstrating myocardial active inflammation." (PMID 39597880, 2024).
Chlamydia infection (1 paper, 2025). "While direct evidence in Chlamydia infection is limited, DSG2 and OCLN are known to regulate epithelial tight junction integrity, and their down-regulation may compromise barrier function and increase susceptibility to infection." (PMID 41042872, 2025).
choriocarcinoma (1 paper, 2025). An aggressive malignant tumor arising from trophoblastic cells. "PLAC1 has been shown to interact with DSG2 in a choriocarcinoma model." (PMID 40607388, 2025).
chronic pancreatitis (1 paper, 2008). A chronic inflammatory process causing damage and fibrosis of the pancreatic parenchyma. "The chronic pancreatitis samples showed staining intensity and distribution similar to the normal pancreatic samples for Dsg1 and Dsg2." (PMID 19091121, 2008).
clear cell carcinoma (1 paper, 2013). "They further demonstrate that knockdown of CD133 by RNA interference (RNAi) results in the downregulation of desmoglein-2, a desmosomal cadherin, and abrogates cell-cell adhesion and tumorigenicity of clear cell carcinoma of the ovary stem cells." (PMID 23864867, 2013).
dementia (1 paper, 2026). Loss of intellectual abilities interfering with an individual's social and occupational functions. "As for Dsg2, its decrease is consistent with the “leaky gut” hypothesis in the context of age‐related diseases such as dementia." (PMID 41524247, 2026).
familial dilated cardiomyopathy (1 paper, 2023). A a genetic form of heart disease that occurs when heart (cardiac) muscle becomes thin and weakened in at least one chamber of the heart, causing the open area of the chamber to become enlarged (dilated). "DSG2 autoantibodies have the potential to be pathogenic and have been associated with ARVC and familial dilated cardiomyopathy." (PMID 37095599, 2023).
fibrosarcoma (1 paper, 2016). A malignant mesenchymal fibroblastic neoplasm affecting the soft tissue and bone. "To assess the role of Dsg2 independent of desmosomes, we employed the HT1080 fibrosarcoma-derived cells." (PMID 26918609, 2016).
Granuloma (1 paper, 2026). A compact, organized collection of mature mononuclear phagocytes, which may be but is not necessarily accompanied by accessory features such as necrosis. "DSG2 (desmoglein) is known to induce pro-proliferative activity in dermal fibroblasts and is highly upregulated in zebrafish and human granuloma." (PMID 41489684, 2026).
heart palpitations (1 paper, 2025). "His daughter (III-1), suffering from heart palpitations, carries both the DSG2 variant inherited from her father and the JUP variant c.1928C>T (p.Thr643Ile) from her healthy mother (II-2)." (PMID 41287789, 2025).
hemorrhagic cystitis (1 paper, 2021). Inflammation of the bladder resulting in bloody urine. "Dsg2 has been specifically implicated as a receptor for group B adenovirus serotypes 3, 7, 11, and 14; of note, serotype 11 is most commonly associated with hemorrhagic cystitis in renal and other transplant recipients." (PMID 33513212, 2021).
Human papillomavirus infection (1 paper, 2022). "And the co-expression genes of PLOD2 and DSG2 also enriched in the Human papillomavirus infection which is inseparable with CC development." (PMID 35154316, 2022).
hyperglycaemia (1 paper, 2022). "To further examine a protective role for DSG2 in β-cell function, we challenged the mice with streptozotocin (STZ), an alkylating agent that targets the insulin-producing β-cells in the pancreas, thus mimicking β-cell loss and hyperglycemia characteristic of type 1 diabetes." (PMID 36309486, 2022).
ichthyosis (1 paper, 2015). Disorders of cornification that are characterized by visible scaling and/or hyperkeratosis of most or all of the skin. "Here, we wanted to assess whether Dsg2 plays a role exfoliative ichthyosis by synergizing with CSTA to modulate cell adhesion." (PMID 25785582, 2015).
inflammatory skin disease (1 paper, 2021). Inflammatory skin disorders covers a broad category that includes many conditions ranging in severity, from mild itching to grave medical health complications These disorders are common in people of all ages and races. "When we compared PSO vs. AD to evaluate desmosome profiling similarities in inflammatory skin diseases, we found that DSG4, DSP, DSG2, and PKP2 displayed less than a two-fold difference in gene expression." (PMID 33995349, 2021).
Left ventricular dilatation (1 paper, 2023). Enlargement of the chamber of the left heart ventricle. "Our results indicate that increasing concentrations of anti-desmoglein-2 antibodies correlate with the degree of left ventricular dilatation in dogs with structural cardiac disease, regardless of whether that disease is ARVC, DCM, or MMVD." (PMID 36977772, 2023).
mesothelioma (1 paper, 2023). A usually malignant and aggressive neoplasm of the mesothelium which is often associated with exposure to asbestos. "The said fact was evidenced by the expression of CAR, DSG-2, and CD46 receptors and PD-L1 in human mesothelioma cell lines." (PMID 38053658, 2023). "All mesothelioma cells lines (MSTO-211H, H226, and Mero-82) expressed high level of CD46 (93%, 99%, and 99%, respectively) and DSG2 (99%, 99%, and 98%, respectively) on their surfaces." (PMID 38053658, 2023).
metastatic melanoma (1 paper, 2016). A melanoma that has spread from its primary site to another anatomic site. "Therefore, DSG2 can be heterogeneously expressed within individuals with metastatic melanoma." (PMID 27340778, 2016).
migraine (1 paper, 2025). "Six proteins were significantly upregulated in migraine with a >1.5 fold change compared to controls and Padj < 0.05 (FAM3C, GOLM1, PSA7, ENPP2, DSG2, TFRC); 3 proteins were significantly downregulated (FGL1, CAH2, AMYP)." (PMID 40852402, 2025).
Moyamoya disease (1 paper, 2024). Moyamoya disease (MMD) is a rare intracranial arteriopathy involving progressive stenosis of the cerebral vasculature located at the base of the brain causing transient ischemic attacks or strokes. "The results of IHC showed that the STA tissue intima of Moyamoya disease was significantly thicker than that of normal control, and the expression of DSG2 was also significantly decreased." (PMID 38326520, 2024). "In this study, we used RNA sequencing, Western blot, and immunohistochemistry to analyze DSG2 levels in the vessels of Moyamoya disease." (PMID 38326520, 2024). "The expression of DSG2 in the STA tissues of Moyamoya disease was lower than that in normal controls." (PMID 38326520, 2024). "We analyzed the gene expression difference of Moyamoya disease by RNA sequencing and found that the expression of DSG2 decreased significantly in Moyamoya disease as confirmed by Western blot and immunohistochemical validation." (PMID 38326520, 2024). "RNA sequencing showed that the mRNA level of DSG2 was significantly decreased in Moyamoya disease compared with normal controls." (PMID 38326520, 2024). "Our results indicate that DSG2 affects PI3K signaling in vascular endothelial cells, and MMP-9 is involved in DSG2-mediated vascular changes in Moyamoya disease." (PMID 38326520, 2024). "RNA sequencing, immunohistochemistry (IHC), and western blotting were used to detect the expression of DSG2 in the superficial temporal artery (STA) tissues of Moyamoya disease." (PMID 38326520, 2024). "Taken together, these results suggest that DSG2 affects PI3K signaling in vascular endothelial cells, and MMP-9 is involved in DSG2-mediated vascular changes in Moyamoya disease." (PMID 38326520, 2024). "This study aimed to investigate the effect of desmoglein-2 (DSG2) on Moyamoya disease and determine the inhibitory effect of DSG2 in vascular remodeling in Moyamoya disease." (PMID 38326520, 2024). "The results of Western blot showed that the expression of DSG2 protein in Moyamoya disease was significantly reduced." (PMID 38326520, 2024). "The main findings of this study are as follows: (a) DSG2 level decreased in patients with Moyamoya disease, (b) DSG2 affects PI3K signaling in vascular endothelial cells, and (c) MMP-9 is involved in DSG2-mediated vascular changes in Moyamoya disease." (PMID 38326520, 2024). "In addition, we concluded that DSG2 is protective for vascular endothelial cells via PI3K signaling, and MMP-9 is involved in DSG2-mediated vascular changes in Moyamoya disease." (PMID 38326520, 2024). "However, the role of DSG2 in Moyamoya disease has never been explored." (PMID 38326520, 2024).
multiple sclerosis (1 paper, 2023). A progressive autoimmune disorder affecting the central nervous system resulting in demyelination. "Finally, astrocyte cluster 8 (MMP7, SERPINA3, GZMA, and CLIC1) and microglial cluster 2 (DSG2 and TNFRSF25) were elevated in multiple sclerosis patients and suggested the pathogenic role of these biomarkers during multiple sclerosis progression." (PMID 37468977, 2023).
nephrolithiasis (1 paper, 2024). The presence of a calculus in the pelvis of the kidney; this is most often composed of mineral salts and proteins. "Differential expression of AXL, HIP1R, JUP, CTNNB1, and DSG2 was confirmed via PRM, suggesting their potential roles in the development and advancement of nephrolithiasis, warranting further exploration." (PMID 39114033, 2024).
nonischemic cardiomyopathy (1 paper, 2024). Forms of cardiomyopathy that are not related to known coronary artery disease. "Researchers found a specific DSG2 variant, p.Arg119Ter, in four patients with nonischemic cardiomyopathy.The study involved genetic analysis of 808 patients, identifying five with DSG2 variants." (PMID 39706847, 2024).
oligodendroglioma (1 paper, 2015). A well-differentiated (WHO grade II), diffusely infiltrating neuroglial tumor, typically located in the cerebral hemispheres. "To analyze DSG2 cell expression in GBM tumors, we stained primary tumors of grade III (Oligodendroglioma) and grade IV (GBM) with antibodies to DSG2 proteins." (PMID 25738357, 2015).
oral squamous cell carcinomas (1 paper, 2020). "It was reported that Dsg2 is upregulated in PV patients’ lesions and that Dsg2 and Dsg3 expression are interdependent in oral squamous cell carcinomas." (PMID 33193387, 2020).
psoriasis (1 paper, 2025). An autoimmune condition characterized by red, well-delineated plaques with silvery scales that are usually on the extensor surfaces and scalp. "Taken together, this study has identified an important link between Dsg2 and NF-κB signaling involved in controlling matrix production and remodeling, which has relevance for multiple processes in the epidermis such as wound healing and psoriasis." (PMID 41244075, 2025).